STAT6 (signal transducer and activator of transcription 6)
Diseases named in the same sentence as STAT6 in open-access papers (continued):
Sharing a sentence is not in itself a finding about the gene and the disease.
asthma (continued). "TMC-264 was originally discovered for its potent, selective inhibitory affect against tyrosine phosphorylation of the transcription factor STAT6, a small molecule target for asthma pathogenesis." (PMID 25379337, 2014). "As allergic, IL-13 driven, asthma is the primary indication for therapeutic STAT6 siRNA, our rationale for this approach was based on findings that respiratory allergy is reflective of an integrated, systemic inflammatory disorder." (PMID 24587331, 2014). "STAT6 gene (human signal transducer and activator of transcription 6) is considered as one of the most promising candidate genes for asthma." (PMID 24790987, 2014). "Sprr2 transcription can be also regulated by IL4/IL13/Stat6, as described in an experimental asthma mouse model." (PMID 23844115, 2013). "Activated STAT6 also regulates the expression of Th2 chemokines that function as asthma indicators when these chemokines are upregulated." (PMID 23861779, 2013). "Epithelial STAT6 expression is fundamental to asthma pathogenesis in which inflammatory changes are found throughout the respiratory tract." (PMID 23402658, 2013). "TSLP can induce multiple signaling pathways in asthma, including STAT6, IL-4, IL-1β and TNFα, p38 and Jun kinase (JNK )." (PMID 24167583, 2013). "This is in accordance with a previous study that found similar levels of STAT6 in PBMCs from normal subjects and patients with extrinsic asthma." (PMID 22401596, 2012). "Interleukin (IL)-13, IL-4, interleukin 4 receptor (IL-4Ra), signal transducer and activator of transcription 6 (STAT6) and tumor necrosis factor-alpha (TNFα) genes are key inflammatory genes in the development of allergic diseases such as asthma." (PMID 22355322, 2012). "Several studies have shown the importance of these signaling molecules in asthma, but the roles of IL-4Rα and STAT6 in modulating specific features of airway inflammation were unclear." (PMID 22014099, 2011). "The lung was chosen as STAT-6 is known to play a key role in pulmonary eosinophilia and airway hyperreactivity in the context of experimental asthma." (PMID 19252738, 2009). "STAT6 is another pathway in the family of STAT that has also been implicated in the development of allergic disease and asthma." (PMID 23675060, 2008). "Many transcription factors (for example NF-κB, AP-1, GATA-3, STAT-1 STAT-6, c-Maf, NFATs and SOCS) have been implicated in the differentiation of Th2 lymphocytes and therefore represent therapeutic targets for asthma." (PMID 18315837, 2008). "In addition, ERBB3, IL1R1, IL1RL2, IL6R, LRRC32, STAT6, and TNFRSF6B have been strongly linked to allergic diseases, such as asthma and rhinitis." (PMID 38773393, 2024). "IL-13/IL-4/JAK/STAT6 is a key signaling pathway essential to type 2 inflammation and allergies, and strategies to target it have proven effective to treat atopic dermatitis, asthma and to prevent itching." (PMID 39345572, 2024). "STAT6 plays a critical role in Th2 lung inflammatory responses and the pathogenesis of asthma." (PMID 37101296, 2023). "Pirfenidone could replace dexamethasone treatment in the current rat model of CYP-induced severe steroid-resistant asthma via inhibiting the M1 macrophage differentiation through modulation of the STAT6/p38 MAPK pathway." (PMID 37048067, 2023). "In particular, when STAT1, STAT3, and STAT6 are activated as transcription factors by inflammatory cytokines, they can induce the expressions of genes and lead to inflammatory conditions such as asthma, rheumatoid arthritis, and AD." (PMID 38258052, 2023). "Given the finding that phosphorylated STAT6 is the primary target for degradation upon PARP-1 inhibition, this represents a unique opportunity to target the transcription factor for degradation during asthma where the IL-4/IL-13/STAT6 pathway is upregulated especially in uncontrolled/severe disease." (PMID 36348405, 2022). "Recent studies showed that STAT6 is critically involved in asthma and lung fibrosis." (PMID 35606692, 2022).
asthma (continued). "We reported that PARP-1 regulates genes whose products are crucial for asthma, in part, by controlling STAT6 integrity speculatively through a calpain-dependent mechanism." (PMID 36348405, 2022). "The IL-4/IL-13/STAT-6 pathway is a well-known key regulator in asthma pathophysiology." (PMID 35743888, 2022). "Given that STAT6 has also been shown to be involved in chronic inflammatory states, such as allergy, asthma, atopic dermatitis, and eosinophilic esophagitis, this may be a major driver of chronic inflammatory changes in the injured brain post-TBI." (PMID 35558731, 2022). "Conversely, STAT6 is a transcription factor present in Th2 cells with ability to induce secretion of IL-4, IL-5, and IL-13, which are responsible for the main features of asthma." (PMID 36685604, 2022). "The prevalence of nonallergic asthma is much higher in the Pakistani population due to signal transducer and activator of transcription 6 (STAT6) polymorphisms." (PMID 34104581, 2021). "Furthermore, inflammatory pathology is supported by the presence of GATA3 and STAT6 in asthma and inflammatory gene clusters in the pathway analysis." (PMID 35386986, 2021). "In this study, we investigated the protective effect of BV extract—which has been clinically applied, rather than its components —on mucus metaplasia in asthma, assessing the effect of BV on IL-13-mediated STAT6 activation and MUC5AC production in the human airway epithelial cell line A549." (PMID 34822557, 2021). "STAT6 is activated by IL-4 and IL-13 and plays a predominant role in the immune system including clearance of helminthic parasites as well as the pathogenesis of allergic disorders like asthma, food allergies, and atopic dermatitis." (PMID 32431691, 2020). "In addition, DClps produced more IL-10 and TGF-β than DCim, leading to dramatic decreases in the phosphorylation of both STAT4 and STAT6, which are critical in initiating Th1- and Th2-mediated immunoinflammatory processes in asthma, respectively." (PMID 32807859, 2020). "In contrast, STAT6-deficient T cells activated by Peyer’s patch B cells did not exert the effects on OVA-induced asthma parameters." (PMID 33584704, 2020). "Recent clinical validations indicate that inhibition of the JAK2/STAT6 signaling pathway may be considered for ovalbumin-induced asthma therapies." (PMID 32512817, 2020). "The IL-4/IL-13/STAT-6 pathway is a key modulator of asthma pathophysiology." (PMID 31637021, 2019). "However, deficiency of SOCS2 was reported to enhance Th2 differentiation in a murine model of allergy and asthma, in which STAT6 and STAT5 were activated, whereas STAT3, which is crucial for Th17 polarization was not." (PMID 31949423, 2019). "This suggests that strong neutrophilia induced by asthma sensitization in STAT-6−/− mice could be sufficient to increase resistance to S. pneumoniae in our model." (PMID 30147700, 2018). "STAT6 small-molecule inhibitors are currently under development for the treatment of asthma and could also be evaluated in the context of ALL." (PMID 29656114, 2018). "However, DNA microarray profile analysis of wild-type and STAT6−/− asthmatic mice showed that a large portion of the transcriptional asthma signature is STAT6 independent." (PMID 30147700, 2018). "As histone acetylation is commonly associated with gene expression, our finding may provide an epigenetic mechanism for the increase in STAT6 expression seen in asthma." (PMID 26243279, 2015). "The data from all of these diverse systems are in agreement and support our hypothesis that LABAs activate STAT6 to promote or exacerbate asthma." (PMID 26605551, 2015). "Furthermore, consistent with the increased recognition that epithelial cells play a fundamental role in asthma pathogenesis, it is notable that STAT6 expression in lung epithelial cells was shown to be exclusively required for IL-13-mediated pathology." (PMID 24587331, 2014).
asthma (continued). "STAT6 expression in lung epithelial cells is exclusively required for IL-13-mediated pathology, consistent with the increasing recognition that epithelial cells play a fundamental role in asthma pathogenesis." (PMID 23402658, 2013). "As a result, STAT6 gene expression is increased and asthma is induced via an IL-4/IL-13 pathway." (PMID 23861779, 2013). "Thus, IL-4/IL-13/signal transducer and activator of transcription 6 (STAT6) pathway becomes promising targets for asthma therapies by using IL-4 receptor antagonists and anti-IL-13 mAbs." (PMID 24204835, 2013). "Countering the argument that aspirin may function in AERD as an IL-4-STAT6 antagonist is the lack of an obvious recognition of its utility in aspirin-tolerant asthma or even allergic rhinitis; disorders that arguably also involve IL-4 and STAT6 expression." (PMID 22262978, 2012). "Home dampness combined with each one of the genes STAT6, IL13 and ADRB2 could also raise the asthma risk." (PMID 22355322, 2012). "Changes in STAT6 phosphorylation paralleled the effects of rapamycin on HDM-induced asthma." (PMID 22685525, 2012). "Home dampness combined with each one of the genes STAT6, IL13 and ADRB2 could raise the asthma risk." (PMID 22355322, 2012). "Further studies with large number of participants are needed to characterise fully the role of the STAT6 proteins in the regulation of gene expression in these cell types and their potential role in the pathogenesis of asthma, because asthma has various phenotypes." (PMID 22401596, 2012). "Moreover, this study, as well as previous ones raises the question of the effectiveness of blocking only the STAT6 pathway as a treatment for asthma." (PMID 21205293, 2011). "CD4+ T helper type 2 (TH2) cells, their cytokines IL-4, IL-5 and IL-13 and the transcription factor STAT6 are known to regulate various features of asthma including lung inflammation, mucus production and airway hyperreactivity and also drive alternative activation of macrophages (AAM)." (PMID 22014099, 2011). "STAT6 has been suggested as a possible new target for asthma treatment." (PMID 21205293, 2011). "This study clearly indicates that alternative STAT6-independent signalling pathways exist that may contribute to asthma pathogenesis." (PMID 21423619, 2011). "STAT-6 mediates many of the biological effects of IL-13 during asthma pathogenesis and fibrosis." (PMID 20738867, 2010). "All of these characteristics of airway remodeling in asthma (eosinophilia, mucous cell metaplasia, airway fibrogenesis) are absent in a model of allergic asthma in STAT-6-deficient mice." (PMID 20738867, 2010). "Furthermore, understanding the role of STAT6 in asthma pathogenesis could lead to the development of targeted therapies." (PMID 40375219, 2025). "Children with the TT genotype or the T allele of the STAT6 rs324011 polymorphism might be at a greater risk of developing asthma than children without this genetic variation." (PMID 40375219, 2025). "Analyzing additional SNPs in STAT6 (e.g., rs324015, rs3024944, rs71802646) and other genes (e.g., IL1RL1, GATA3, ADAM33, TSLP, FOXO3a) would expand the scope of genetic analysis and provide a comprehensive understanding of asthma susceptibility in the population." (PMID 40375219, 2025). "In addition, RAGE is also required for the IL-4-/IL-13-dependent phosphorylation of the signal transducer and activator of transcription 6 (STAT6), resulting in chemokine production, airway inflammation, and mucus metaplasia, therefore contributing to the severity of asthma." (PMID 39766257, 2024). "Therefore, it is reasonable to speculate that STAT6-related signaling pathways might be involved in the pathogenesis of AD and asthma." (PMID 35177102, 2022).
asthma (continued). "In addition, the STAT6 SNP rs324015 was associated with reduced SEA-specific IFNγ when comparing genotypes, and this SNP has been previously associated with reduced asthma risk and reduced IgE, thereby indicating that this polymorphism results in a dampening of TH2 responses." (PMID 35759449, 2022). "In mice, ORMDL3 expression has been shown to be induced by allergen, IL-4 and IL-13 via STAT6 and in bronchial epithelial cells, overexpression of ORMDL3 has been shown to trigger activating transcription factor 6 (ATF6), which has also been implicated in airway remodeling in asthma." (PMID 35386986, 2021). "Surprisingly, in our model, CD3 and STAT-6 deficiency did not impair resistance to S. pneumoniae infection following asthma sensitization, demonstrating that this phenomenon is induced by a route that is completely different from that of asthma-induced Brucella susceptibility." (PMID 30147700, 2018). "Consequently, it was reported that IL-4/STAT-6 pathway is involved in asthma pathogenesis because STAT-6 activation lead to the differentiation of naïve T-cells into Th2 effector cells, and it regulates the production of Th2 chemokine induced by IL-4 and IL-13." (PMID 28630596, 2017). "Given our recent findings correlating asthma with biomarker gene expression in primary human nasal epithelial cells, we hypothesised that intra-nasal exposure would provide a simpler, relevant approach to the analysis of STAT6 siRNA activity in vivo." (PMID 24587331, 2014). "However at present the ability of glucocorticoids to target STAT6 action in the lower airways is unknown and may determine whether inhibition of STAT6 activity may be a new therapeutic target for anti-asthma drugs." (PMID 22401596, 2012). "Another study revealed that genistein modulates the transcription factors STAT6, GATA3, and T-bet, attenuating airway allergic inflammation in a murine asthma model." (PMID 39263346, 2024). "The IL-4/IL-13/STAT6 pathway induces expression of inflammatory chemokines such as CCL11, CXCL1, and CXCL3 and is a central pathway in the pathophysiology of asthma, especially airway hyperresponsiveness." (PMID 35281012, 2022). "Drugs that target MUC5AC (ENSITUXIMAB) and STAT6 (CHEMBL363332 and CHEMBL1374370) have emerged as potential avenues of future research via repurposing for severe asthma and show these two proteins are viable therapeutic targets." (PMID 35386986, 2021). "Nemeth reported that Th2-related cytokines activated the signal transducer and activator of transcription 6 (STAT6) pathway in BM-MSCs, which elevated their production of TGF-β, which in turn contributed to the attenuation of asthma in mice." (PMID 34635172, 2021). "Moreover, STAT6 deficient Treg-of-B (P) cells could not alleviate inflammation in an animal model of asthma in vivo." (PMID 33584704, 2020). "Recently, the true efficacy of siRNA directed against particular targets, such as STAT6, PAI-1, and Syk for the treatment of asthma was demonstrated through appropriate in vitro and in vivo studies." (PMID 31979001, 2020). "Surprisingly, asthma-induced resistance to S. pneumoniae is also observed in sensitized CD3−/− C57BL/6 mice and STAT-6−/− BALB/c mice, demonstrating that the protective effect of asthma is independent of Th2 CD4+ T cells." (PMID 30147700, 2018). "STAT-6 and GATA-3 are reported to be central players in PARP-1-mediated eosinophilic inflammation in asthma." (PMID 28974953, 2017). "Different transcription factors, such as STAT-6, GATA-3, activator protein 1 (AP-1), and NF-κB, are involved in the pathogenesis of asthma." (PMID 28974953, 2017). "By searching PubMed, NFKB1, STAT6, E2F1, USF1, and CBFB were the verified asthma-related TFs, while NFKB1 and STAT6 were the newly discovered asthma-related genes in 2013." (PMID 24790987, 2014). "NFKB1, STAT6, and E2F1 were the verified asthma-related TFs in PubMed, and they were discovered to exert regulatory impact in this study." (PMID 24790987, 2014).
asthma (continued). "Home dampness combined with each one of the genes STAT6, IL13 and ADRB2 raised the testing accuracy on asthma higher than 57.34%." (PMID 22355322, 2012). "Adoptive transfer of wild type TH2 cells into mice is an effective tool to bypass the role of STAT6 and IL-4Rα in TH2 cell differentiation, while allowing the study of these signaling molecules in the effector phase of asthma." (PMID 22014099, 2011). "A primary role for IL-13 in asthma and Th2-mediated fibrogenic reactions is the production of TGF-β1 via a STAT-6-dependent mechanism." (PMID 20738867, 2010). "Our results showed that, during acute asthma exacerbation, hsa‐miR‐155‐5p in AEC‐Exos regulates the differentiation of CD4+ T cells into Th2 type inflammation through the SIRT1 pathway, which was mediated through enhanced expression of STAT6 and GATA3." (PMID 38938285, 2024). "There is evidence that treatment of allergic asthmatics with inhaled steroids was able to reverse the high levels of IL-5, IL-13 and IL-9 produced by ILC2s via STAT3, STAT5, STAT6, JAK3 and MEK signaling pathways, which was accompanied by better asthma control." (PMID 39452061, 2024). "Overall, our results found that BGE inhibits allergic airway inflammation by negatively regulating the activation of PKCθ and asthma-related transcription factors (NFAT, NF-κB, GATA3, and STAT6) in mice with allergic airway inflammation as well as in EL4 cells." (PMID 37569348, 2023). "Although distinct endotypes (Th2-High and Th2-Low) have been described in asthma, we focus here on the importance of the IL-13/SPDEF/STAT6 pathway (interleukin-13/SAM pointed domain-containing ETS transcription factor/signal transducer and activator of transcription 6)." (PMID 35269434, 2022). "Therefore, the study concludes that IL-4 and STAT6 are potential targets for preventing infection-induced AHR and severity of asthma in future life." (PMID 34226412, 2021). "Since the activation of STAT6 signaling has a critical role in allergic pulmonary inflammation, the STAT6-dependent induction of HIMF in the alveolar epithelium during pulmonary inflammation and fibrosis suggests that HIMF is involved in asthma pathogenesis." (PMID 34336840, 2021). "Within examined ten genes in cord blood, the methylation status of ORMDL1 and STAT6 in healthy farmers 'children in comparison with nonfarmers' children with asthma was distinguishable." (PMID 33781317, 2021). "The results reveal that dexamethasone and Majie Cataplasm could prohibit the overexpression of STAT6 mRNA and GATA-3 mRNA in the asthma model group, while the effect of the two drugs rarely align for T-bet mRNA." (PMID 32489402, 2020). "Thus, our findings highlight a role for the PGE2-EP4-AKT-PPARγ-STAT6 signaling in IgE response, highlighting the therapeutic potential of combined application of EP4 and PPARγ agonists in asthma." (PMID 32636842, 2020). "An association with asthma was only seen in non-farming offspring for hypermethylated cord blood ORMDL3 and STAT6." (PMID 26052354, 2015). "However, it remains unclear whether STAT6 and/or NF‐κB influence the development of pulmonary CCL17 and CCL22 in the context of rhinovirus (RV) infection and asthma." (PMID 39508721, 2024). "Targeting activated STAT6 for degradation may not be unique to asthma; rather, it can be applied to cancer as well." (PMID 36348405, 2022). "It has been reported that total STAT6 expression is increased in the bronchial epithelium of asthma patients compared to controls, but others could not reconfirm this result." (PMID 27716212, 2016). "Our data further support these observations because although glucocorticosteroids have a clear anti-asthmatic effect, LABAs activate STAT6 even in the presence of glucocorticosteroids and are alone sufficient to induce asthma-like airway obstruction in the complete absence of allergen provocation." (PMID 26605551, 2015). "However, the effect of IL-4Rα or STAT6 on FIZZ1/YM1 protein induction in an asthma model has not yet been studied." (PMID 22014099, 2011).